LEF1 (lymphoid enhancer binding factor 1)
Diseases named in the same sentence as LEF1 in open-access papers (continued):
Sharing a sentence is not in itself a finding about the gene and the disease.
endometrial cancer (9 papers, 2012 to 2023). Primary or metastatic malignant neoplasm involving the endometrium (mucous membrane that lines the endometrial cavity). "Our study provides new insights into the biology of high‐risk endometrial cancer and suggests that targeting LEF1 may be worthy of investigation in this treatment‐resistant cancer subgroup." (PMID 37589076, 2023). "This relationship between mutated β-catenin leading to activated Lef1 gave us cause to speculate that Lef1 may be dysregulated in endometrial cancer." (PMID 22792274, 2012). "Hence, LEF1 has been implicated in tumorigenesis and progression of several neoplasms, including endometrial cancer, where it has been suggested that it may have a potential value as a prognostic biomarker." (PMID 34420090, 2021). "GSEA of high‐risk endometrial cancers from TCGA (CN high UCEC and UCS) revealed enrichment of LEF1 signalling in cases with FBXW7 missense driver mutation (Dataset EV7)." (PMID 37589076, 2023). "Taking an agnostic approach, we identified enrichment of a gene signature corresponding to the Wnt pathway effector LEF1 in Fbxw7 mutant mouse endometrial cancers." (PMID 37589076, 2023). "Consistent with our findings in human endometrial cancers, Lef1 was overexpressed in the glandular component of all tumors tested." (PMID 22792274, 2012). "We have observed high levels of gland-specific Lef1 expression in both the mouse model of endometrial cancer and in human endometrial tumors." (PMID 22792274, 2012). "Lef1 is overexpressed in both mouse and human endometrial cancer specimens, and certain Lef1 downstream targets are activated through this mechanism, specifically cyclin D1 and MMP7." (PMID 22792274, 2012). "Additional studies are required to further elucidate the role of Lef1 in normal gland regulation and endometrial cancer formation." (PMID 22792274, 2012). "Recently, for endometrial cancer similar observations have been described confirming promoter-binding sites for the Wnt/β-catenin inducing transcription factor LEF-1 and, interestingly, also for the EMT inducing transcription factors SNAI1 and SNAI2." (PMID 22295114, 2012). "We also noted that Lef1 protein was expressed at higher levels in endometrial cancers within mice and humans when compared to normal endometrium." (PMID 22792274, 2012). "We next examined expression of the Lef1 target cyclin D1 in the developing mouse uterus because cyclin D1 levels are elevated in patients with endometrial carcinoma." (PMID 22792274, 2012). "Our study is one of the first to examine the role of LEF1 in the development of endometrial glands and the expression within endometrial carcinomas." (PMID 22792274, 2012). "Mutations of the CTNNB1 gene, which commonly occur in 12–25% of endometrial carcinomas, typically result in increased cytoplasmic and nuclear accumulation of β-catenin, which subsequently leads to activation of Lef1 and Tcf family members." (PMID 22792274, 2012). "Taking these observations together with our data, it appears plausible that failure of Fbxw7 missense‐mutant endometrial cancers to degrade Lef1 may contribute to tumorigenesis and EMT in our GEMM." (PMID 37589076, 2023). "By transcriptomic analysis, we identify LEF1 signalling as upregulated in Fbxw7/FBXW7‐mutant mouse and human endometrial cancers, and in human isogenic cell lines carrying FBXW7 mutation, and validate LEF1 and the additional Wnt pathway effector TCF7L2 as novel FBXW7 substrates." (PMID 37589076, 2023). "The role of LEF1 protein overexpression in the carcinogenesis of endometrial cancer may be related to the modulation of cell surface adhesion proteins, influencing the prognosis of this tumor." (PMID 34485158, 2021). "A study with LEF1 knockout mice demonstrated its importance in endometrial cancer carcinogenesis." (PMID 34485158, 2021). "We hypothesized that Lef1 is required for endometrial gland formation within the uterus and is overexpressed in endometrial cancer." (PMID 22792274, 2012).
endometrial cancer (continued). "Thus we believe not only that Lef1 is important in endometrial-gland formation, but also that dysregulated Lef1 plays a role in the etiology of endometrial cancer." (PMID 22792274, 2012). "Here we report on the role of the Wnt pathway and Lef1 specifically in endometrial cancer, introducing a role for overexpression of full-length Lef1 in the etiology of endometrial cancer, and for controlled expression of Lef1 in development of the endometrial gland." (PMID 22792274, 2012). "Additionally, the four genes (FN1, DUSP4, LEF1, and SMAD9) identified can shed light on the mechanisms of recurrence in endometrial cancer." (PMID 34485158, 2021). "Lef1 is overexpressed in endometrioid endometrial carcinomas compared to nonendometrioid endometrial carcinomas, and where the Lef1 downstream targets are activated through cyclin D1 and MMP7." (PMID 34068065, 2021). "Another candidate that has not yet been evaluated is LEF1, a nuclear effector of the Wnt/beta-catenin pathway, overexpressed in CTNNB1-mutated tumours according to the Clinical Proteomic Tumour Analysis Consortium (CPTAC) proteogenomic characterisation of endometrial cancer." (PMID 34420090, 2021). "Similarly, quantitative real-time PCR data demonstrate that Lef1 RNA expression is higher in the endometrium of patients with proliferative, non-cancerous disorders and in patients with endometrial cancer than in endometrium from normal postmenopausal patients." (PMID 22792274, 2012).
liver cancer (8 papers, 2015 to 2025). An epithelial or non-epithelial malignant neoplasm that arises from the liver. "Targeting the LEF1-mediated EMT process can reverse lenvatinib resistance in liver cancer cells." (PMID 40810004, 2025). "Comparably, analysis of available human liver cancer cell lines revealed a strong positive correlation between PRAME and the expression of TWIST or LEF1." (PMID 37173882, 2023).
ovarian carcinoma (8 papers, 2003 to 2024). A malignant neoplasm originating from the surface ovarian epithelium. "Assessment of representative sections from the entire fallopian ducts of 11 patients with high risk of developing ovarian cancer revealed presence of cytoplasmic/nuclear βcatenin, LEF1, Pax8 and Stathmin 1-positive precursor lesions in all of the patients (SFigure 1)." (PMID 27588493, 2016). "Quercetin treatment inhibited cell growth in cell lines from cancer types where Lef1 expression was high, such as colon and ovarian cancer cells." (PMID 32492961, 2020). "Constitutive β-catenin/Lef-1-mediated transcriptional activity has been detected in four out of 19 investigated ovarian cancer cell lines." (PMID 14520463, 2003). "In addition, a previous study revealed that LEF1 was consistently expressed in the serous tubal intraepithelial carcinoma, the precursor region of ovarian cancer." (PMID 38338902, 2024). "In ovarian cancer, the expression of TAP1 is related to MEF2A, LEF1, while MEF2A can promote tumor cell metastasis by inducing epithelial-mesenchymal transformation and activating Wnt/β-catenin signal pathway." (PMID 36419887, 2022). "Further, we verified the expression of TAP1-related transcription factors (MEF2A and LEF1) and found that TAP1 was closely related to ovarian cancer metastasis in vitro and in vivo." (PMID 34957213, 2021). "Immortalised human ovarian surface epithelium and ovarian cancer cell cells (OVCAR-3) expressed β-catenin, APC, GSK3β and Lef-1." (PMID 14520463, 2003). "Even though higher levels of Lef-1 were demonstrated in malignant ovarian tumours, this increase was not significant compared to normal and benign ovarian tumours." (PMID 14520463, 2003).
oral squamous cell carcinoma (7 papers, 2017 to 2025). "Moreover, the conserved LEF1 recognition site is present on the promoter region of MMP-7 and is bound directly by LEF1 in oral squamous cell carcinoma cell lines and human oral squamous cell carcinoma tissues." (PMID 28757546, 2017).
osteoarthritis (7 papers, 2012 to 2022). A noninflammatory degenerative joint disease occurring chiefly in older persons, characterized by degeneration of the articular cartilage, hypertrophy of bone at the margins and changes in the synovial membrane. "To determine whether changes in the Wnt-signaling pathway are associated with osteoarthritis, we evaluated the expression levels of Wnt transcription factors, LEF-1 and TCF-4, and phospho-β-catenin in osteoarthritic and normal articular chondrocytes." (PMID 22513174, 2012). "For instance, LEF1 mediated osteoarthritis progression via the NF-κB signaling pathway." (PMID 34096776, 2021). "According to the bioinformatics analyses, we hypothesized that LEF1 regulated the progression of osteoarthritis." (PMID 32732957, 2020). "The essential role of LEF1 in osteoarthritis was demonstrated in the previous study." (PMID 32732957, 2020).
viral infection (7 papers, 2016 to 2025). "We used the 39k promoter, which is induced by viral infection, to express Cas9 and the U6 promoter to express four small guide RNA targeting the genes encoding BmNPV late expression factors 1 and 3 (lef-1 and lef-3, respectively), which are essential for viral DNA replication." (PMID 35062262, 2021). "The results showed that as the viral infection progressed, the expression of Wnt/β-catenin pathway-related genes β-catenin, TCF-4, LEF-1, c-Myc, and Cyclin D1 were significantly upregulated in RB1B infection group." (PMID 38638910, 2024). "As summarized in this review, Tfh cell-related transcription factors including Bcl6, IRF4, STAT1/STAT4/STAT5, T-bet, TCF-1, LEF-1, TOX2, Bach2, FOXP1, and KLF2 are all involved in the virus infection." (PMID 32766317, 2020). "While Bcl6 also displayed a distinct motif enrichment pattern, its role appears more prominent in the D8MPEChi population compared to Tcf7 and Lef1, this is consistent with recent finding that Bcl6 is required for the generation of CD8+ memory precursors upon acute viral infection." (PMID 39804040, 2025). "We also observed a population of naïve CD4 T cells (denoted ‘Xcl1+ naïve’) expressing Lef1 and Sell genes along with Xcl1, which is a ligand of XCR1 (or G protein-coupled receptor 5, GPR5), with increased expression on NK and CD8+ T cells during virus infection." (PMID 40096073, 2025).
acute promyelocytic leukemia (6 papers, 2014 to 2020). An aggressive form of acute myeloid leukemia (AML), characterized by arrest of leukocyte differentiation at the promyelocyte stage, due to a specific chromosomal translocation t(15;17) in myeloid cells. "We evaluated the prognostic significance of LEF1 expression in 78 adult acute promyelocytic leukemia (APL) patients." (PMID 24378360, 2014). "However, other studies showed that low LEF1 level is a poor prognostic factor in myelodysplastic syndromes, AML, acute promyelocytic leukemia of adult patients, and childhood ALL." (PMID 31929803, 2019).
bladder cancer (6 papers, 2020 to 2025). "LSD1 up-regulates LEF1 (lymphoid enhancer binding factor 1) through β-catenin to promote the epithelial–mesenchymal transition of bladder cancer and tumor progression." (PMID 40028036, 2025). "The enzyme lysine-specific demethylase 1 (LSD1) also promotes bladder cancer progression by enriching LEF1 expression and improving EMT." (PMID 39200196, 2024). "LSD1 (lysine-specific demethylase 1) promotes bladder cancer progression by upregulating LEF1 and enhancing EMT." (PMID 34639214, 2021). "miR-34a targets identified in the context of bladder cancer cells include CD44 and TCF1 and LEF1." (PMID 33114775, 2020).
COVID-19 (6 papers, 2020 to 2025). A disease caused by infection with severe acute respiratory syndrome coronavirus 2. "LEF1 and Notch 1 were able to distinguish severe from mild COVID-19 in the CD8 subset." (PMID 38702425, 2024). "Evidence of T-cell dysregulation demonstrated by immunohistochemical paucity of FOXP3+, Tbet+ and LEF1+ positive T-cells and a downregulation of key genes responsible for T-cell crosstalk, maturation and migration as well as a reactivation of herpes viruses in 6 COVID-19 lymph nodes (EBV, HSV)." (PMID 34966385, 2021). "Downregulation of JUNB and LEF1, and upregulation of RUNX3 was observed in all three ILC subsets from COVID-19 patients." (PMID 39026668, 2024). "Performing this analysis for the COVID-19 patients demonstrated clear B- and T-cell clusters, defined by expression of TCF7, LEF1 (clusters 0 and 1), CD74, CD79A (clusters 2 and 3), IL7R (cluster 4) and CCL5, NKG7, GNLY (cluster 6)." (PMID 33884369, 2021).
neuroblastoma (6 papers, 2009 to 2023). Neuroblastoma (NB) is the most common solid, extracranial childhood tumor. "Furthermore, MAPK and Wnt-associated genes (including LEF1) have been shown to be recurrently mutated in relapsed neuroblastoma." (PMID 28187790, 2017). "The inference from our work that Wnt signalling may have a pro-differentiation and tumour suppressive influence is supported by the recent identification of Wnt pathway mutations in neuroblastoma, which include probable loss of function mutations of LEF1 and VANGL1." (PMID 29505958, 2018). "In another study, overexpression of lymphoid enhancer-binding factor 1 (LEF1) by the CRISPR/Cas9 system in GD2-CAR NKT cells showed superior control in neuroblastoma xenograft mouse models." (PMID 37158883, 2023). "TCF7L2 and LEF1 are likely involved in the genesis of neuroblastoma, similar to TCF7L2 driving c-MYC-dependent intestinal tumorigenesis, but subsequently were sharply downregulated in MNA tumours and cell lines from metastatic neuroblastomas." (PMID 27531891, 2016). "Similarly, when we transiently transfected into N2a-m neuroblastoma cells with Δ56LEF-1 in combination with pENP1 Luc, the luciferase expression estradiol-mediated was severely reduced by the expression of LEF1-mutant." (PMID 19360103, 2009). "The negative correlation between MYCN expression and LEF1 and TCF7L2 expression seen in the cell lines was also observed in the neuroblastoma tumours, confirming the functional MYCN-Wnt interactions revealed in the cell line data." (PMID 27531891, 2016).
sebaceous tumors (6 papers, 2008 to 2022). "Our findings reveal that SC-specific expression of mutant Lef1, which mimics mutations found in human sebaceous tumours, drives sebaceous tumour formation." (PMID 25608467, 2015). "Recent studies have demonstrated sebaceous tumors harboring LEF1 mutations interfere with β-catenin-binding domain of LEF1 and transcriptional activation." (PMID 18226260, 2008). "Human sebaceous tumors have been reported to contain LEF-1 N-terminal domain mutations with decreased ability to interact with β-catenin, and expression of a LEF1 construct lacking the first 32 aa driven by the keratin 14 promoter provoked the formation of sebaceous skin tumors in mice." (PMID 23966864, 2013). "In particular, lineage-tracing experiments demonstrated that hair follicle bulge stem cells constitute one cell of origin for mutant lymphoid enhancer-binding factor 1 (Lef1)-driven sebaceous tumors (K14ΔNLef1 transgenic mice)." (PMID 36439142, 2022). "Astonishingly, expression of mutant Lef1 was higher in CD34+/Itga6high SCs from K14ΔNLef1 mice indicating that lower expression levels of mutant Lef1 driven by the K15 promoter allow for initiation of sebaceous tumours, which differ with respect to morphology, differentiation and aggressive growth." (PMID 25608467, 2015).
colonic adenocarcinoma (5 papers, 2010 to 2024). "LEF1 is a regulator that is closely associated with tumor malignancy and is usually upregulated in cancers, including colonic adenocarcinoma." (PMID 34639214, 2021). "The underlying molecular mechanisms of LEF1 regulation for colonic adenocarcinoma progression remain unknown." (PMID 34639214, 2021). "LEF1 increases colonic adenocarcinoma cells’ motility by remodeling the lamellipodia/filopodia and the polymerization of F-actin/β-tubulin." (PMID 39200196, 2024). "LEF1 maintains the viability and growth of colonic adenocarcinoma cells through improving proliferation and Lamin B1 expression, and reducing apoptosis." (PMID 39200196, 2024). "LEF1 suppresses the expression of epithelial/endothelial–mesenchymal transition-relevant genes, which contributes to the malignancy of colonic adenocarcinomas." (PMID 36975604, 2023). "Our study provided evidence of the roles LEF1 played in colonic adenocarcinoma progression, and suggest LEF1 as a potential target for colonic adenocarcinoma therapy." (PMID 34639214, 2021). "Our results indicate that downregulated LEF1 impairs Lamin B1 expression and Lamin B1 plays a role in the oncogenesis and development of colonic adenocarcinoma." (PMID 34639214, 2021). "LEF1 maintains the viability and growth of colonic adenocarcinoma cells through increasing proliferation, Lamin B1 expression, and decreasing apoptosis." (PMID 34639214, 2021). "In this study, we constructed LEF1 shRNA expression plasmids to estimate the roles of LEF1 in regulating the cell behaviors in colonic adenocarcinoma cells." (PMID 34639214, 2021). "LEF1 expression was distinctly and significantly upregulated in colonic adenocarcinoma samples compared to normal colonic tissues." (PMID 34639214, 2021). "In summary, our study has demonstrated that LEF1 enhances the motility of colonic adenocarcinoma cells via remodeling of lamellipodia/filopodia and the polymerization of F-actin/β-tubulin." (PMID 34639214, 2021). "Overall, the current results demonstrated that LEF1 plays a pivotal role in maintaining the malignancy of colonic adenocarcinoma by remodeling motility correlated microstructures and suppressing the expression of EMT-relevant genes." (PMID 34639214, 2021). "Abnormal expression of LEF1 has been correlated with various tumors including colonic adenocarcinoma." (PMID 34639214, 2021). "The molecular mechanisms regulating LEF1 in the advancement of colonic adenocarcinoma are currently unknown." (PMID 39200196, 2024). "LEF1 can be considered a novel biomarker for the evaluation and therapy of colonic adenocarcinoma." (PMID 34639214, 2021). "Combining other reports with our results in the current study, LEF1 may enhance the malignancy of colonic adenocarcinoma cells intermediated by the activated Wnt/Notch signal crossing talk." (PMID 34639214, 2021). "The results suggest that LEF1 might play a carcinogenic role in colonic adenocarcinoma." (PMID 34639214, 2021). "To demonstrate the potential functions of LEF1 in colonic adenocarcinoma, we used IF and GEPIA to assess LEF1 expression levels between tumor tissues and paired normal tissues." (PMID 34639214, 2021).
congenital neutropenia (5 papers, 2010 to 2018). "In particular, our system does not take into account the possible involvement of certain transcription factors in regulation of mutated elastase, notably LEF1, which had been shown to be dysregulated in congenital neutropenia." (PMID 27942017, 2016). "This suggests that the decreased expression of LEF1 is more a proteic consequence to some mutations causing congenital neutropenia." (PMID 21595885, 2011). "Reconstitution of LEF1 in early hematopoietic progenitors of individuals with congenital neutropenia corrected the defective myelopoiesis and resulted in the differentiation of these progenitors into mature granulocytes." (PMID 21190562, 2010). "However, constitutively active STAT5 (caSTAT5a) and not wild-type STAT5a is associated with inhibition of lymphoid enhancer-binding factor 1 (LEF-1) in CD34 + cells of congenital neutropenia (CN) patients." (PMID 29593731, 2018).